PRMT2 (protein arginine methyltransferase 2)
Description:
Arginine methyltransferase that methylates the guanidino nitrogens of arginyl residues in proteins such as STAT3, FBL, histone H4. Acts as a coactivator (with NCOA2) of the androgen receptor (AR)-mediated transactivation. Acts as a coactivator (with estrogen) of estrogen receptor (ER)-mediated transactivation. Enhances PGR, PPARG, RARA-mediated transactivation. May inhibit NF-kappa-B transcription and promote apoptosis. Represses E2F1 transcriptional activity (in a RB1-dependent manner) (By similarity). May be involved in growth regulation (By similarity). Involved in C15ORF39-mediated inhibition of the microglial inflammatory responses through suppression of NF-kappa-B signaling, thereby reducing the production of pro-inflammatory cytokines.
Synonyms: HRMT1L1; MGC111373
Tractability: PROTAC: ubiquitination databases record sites on it; its protein half-life has been measured.
Gene: Protein-coding gene on chromosome 21 (46,635,595 to 46,665,698, forward strand). Ensembl gene ENSG00000160310.
Subcellular location: Cytoplasm (Isoform 1); Nucleus; Nucleus (Isoform PRMT2Alpha); Cytoplasm (Isoform PRMT2Beta); Nucleus, nucleolus; Nucleus (Isoform PRMT2Gamma); Cytoplasm (Isoform PRMT2L2)
Subcellular location (Human Protein Atlas): Cytosol; Nucleoplasm
Gene Ontology:
Molecular function: histone methyltransferase activity; nuclear androgen receptor binding; nuclear estrogen receptor binding; nuclear progesterone receptor binding; nuclear retinoic acid receptor binding; nuclear thyroid hormone receptor binding; peroxisome proliferator activated receptor binding; protein binding; protein homodimerization activity; transcription coactivator activity; histone H3 methyltransferase activity; histone H3R8 methyltransferase activity; protein-arginine N-methyltransferase activity; protein-containing complex binding; methyltransferase activity; protein-arginine omega-N asymmetric methyltransferase activity
Biological process: negative regulation of canonical NF-kappaB signal transduction; negative regulation of inflammatory response; positive regulation of DNA-templated transcription; regulation of androgen receptor signaling pathway; negative regulation of G1/S transition of mitotic cell cycle; chromatin remodeling
Cellular component: cytoplasm; cytosol; nucleoplasm; nucleus; nucleolus
Genetic constraint (gnomAD): Loss-of-function variants: 26 observed, 54.02 expected, observed/expected ratio (o/e) 0.48, 90% interval 0.35 to 0.67. The upper end of that interval is the gene's LOEUF score, 0.67, which puts it in group 2 of 6, group 1 being the genes least tolerant of losing a copy. Missense variants: 472 observed, 556.36 expected, observed/expected ratio (o/e) 0.85, 90% interval 0.79 to 0.92. Synonymous variants: 219 observed, 216.59 expected, observed/expected ratio (o/e) 1.01, 90% interval 0.9 to 1.13.
Homologues: Orthologues: chimpanzee PRMT2 (99% identical), macaque PRMT2 (98% identical), rabbit PRMT2 (91% identical), rat Prmt2 (89% identical), dog PRMT2 (88% identical), mouse Prmt2 (88% identical), pig PRMT2 (88% identical), guinea pig PRMT2 (81% identical), tropical clawed frog prmt2 (56% identical), zebrafish prmt2 (52% identical), Drosophila melanogaster Art8 (27% identical). Paralogues in human: PRMT6 (30% identical), PRMT3 (30% identical), CARM1 (29% identical), PRMT8 (27% identical), PRMT1 (26% identical), PRMT9 (21% identical), PRMT7 (18% identical).
Diseases named in the same sentence as PRMT2 in open-access papers:
PRMT2 is named in the same sentence as 41 diseases in open-access papers, as found by Europe PMC text mining. Sharing a sentence is not in itself a finding about the gene and the disease. The quoted sentences say what the papers report.
breast cancer (16 papers, 2014 to 2025). A primary or metastatic malignant neoplasm involving the breast. "PRMT2 regulates breast cancer progression as well, the loss of the protein leading to increased cyclin D1 expression, resulting in cancer progression." (PMID 40869229, 2025). "Three novel PRMT2 splicing variants, PRMT2α, PRmt2β, and PRMT2γ, were isolated in breast cancer cells." (PMID 38911125, 2024). "The loss of PRMT2 nuclear expression in breast cancer cells is linked to increased cyclin D1 expression via indirectly binding to the AP-1 site on the cyclin D1 promoter, thus promoting breast tumor cell proliferation." (PMID 34833139, 2021). "In particular, alternatively spliced variants of PRMT2 were related to survival and the invasiveness of breast cancer cells, while high expression of RARG and HOXA9 has been observed in human hepatocellular carcinomas and acute leukemia." (PMID 24401680, 2014). "Furthermore, the PRMT2 variant is able to bind estrogen receptor α both in vivo and in vitro, thereby playing a role in the progression of breast cancer." (PMID 38911125, 2024). "However, other studies indicated that the loss of PRMT2 may be essential for increasing the invasiveness of breast cancer." (PMID 36982660, 2023). "When PRMT2 is downregulated in breast cancer, tamoxifen, a commonly used selective-estrogen receptor modulator, is rendered ineffective as well." (PMID 40869229, 2025). "Previous studies also indicated that the role of PRMT2 in breast cancer progression remains controversial." (PMID 36982660, 2023). "Interaction signals of Ifi204 with HIF1α and that with PRMT2 were clearly observed in almost 80% of adipocytes adjacent to mammary tumor cells." (PMID 35593921, 2022). "PRMT2 was able to reverse tamoxifen resistance in breast cancer cells generated by ER-α36, an estrogen receptor isoform lacking transcription activation functions AF-1 and AF-2 but still containing the DNA-binding domain and most of the hormone-binding domain." (PMID 34833139, 2021). "Recently, PRMT2 levels were found to be decreased in breast cancer cells, while knockdown of PRMT2 correlated with increased expression of both p21 and cyclin D1 indicating a regulatory role for PRMT2 in cell cycle progression." (PMID 29568320, 2018). "The mRNA expression analysis of PRMT2 showed a negative median range in patients with breast cancer, and the high-risk group of GC1 reflected disputable consequences in this study." (PMID 36982660, 2023). "Although PRMT2 has been reported to affect breast cancer and glioblastoma progression, its role in renal cell cancer (RCC) remains unclear." (PMID 37173306, 2023). "The increased expression of the total amount of PRMT2 reported in breast cancer tissue could be explained by the high level of PRMT2 in the cytoplasm, since PRMT2 is clearly decreased in cell nuclei compared with normal breast tissue." (PMID 34833139, 2021). "While these studies all highlighted a critical role of PRMT2 expression in breast cancer, the mechanism remains widely unknown." (PMID 34833139, 2021). "Furthermore, PRMT2 is aberrantly expressed in several cancer types, including breast cancer and glioblastoma." (PMID 34833139, 2021). "Therefore, it is necessary to further study the function of PRMT2 in breast cancer." (PMID 36982660, 2023). "Moreover, it also agrees well with growth inhibition exerted by PRMT2 in breast cancer." (PMID 34439753, 2021). "In glioblastoma, breast cancer, and hepatocellular carcinoma (HCC), PRMT2 acts as a putative oncogene, with its high expression promoting cell proliferation and inhibiting apoptosis through catalyzing H3R8me2a (such as activating Bcl2 expression)." (PMID 41154773, 2025). "From the GEO DataSets GSE42568, we found that PRMT1, PRMT2, and CARM1 were highly expressed in breast cancer cells." (PMID 38476024, 2024).
breast cancer (continued). "Specifically, decreased expression has been shown to improve the prognosis of breast cancer and HCC patients, Alternatively, the presence of PRMT2 has been shown to inhibit NF-κB response and induce apoptosis by blocking the export of IκBα." (PMID 38033034, 2023). "We also analyzed the expression patterns of PRMT subtypes in patients with breast cancer, and the results validated that PRMT1, PRMT2 and PRMT4 were elevated in patients with TNBC compared with levels in those with non-TNBC." (PMID 34683150, 2021). "In humans, in addition to the full-length PRMT2 expressed from a gene of eleven exons, six alternatively spliced PRMT2 isoforms have been detected (UniProtKB–P55345) and four of them (PRMT2L2, PRMT2α, β, and γ) have been isolated from breast cancer cells." (PMID 34833139, 2021). "Although several reports have shown that PRMT2 expression is correlated with breast cancer and glioblastoma (GBM) progression, there is no report on PRMT2 function in RCC or other types of cancers." (PMID 37173306, 2023).
glioblastoma (6 papers, 2018 to 2025). The most malignant astrocytic tumor (WHO grade IV). "It was later demonstrated that PRMT2 overexpression and the H3R8me2a mark were linked to oncogenic transcriptional programming in glioblastoma multiforme, hepatocellular carcinoma, and renal cell carcinoma, in each case strongly correlating with disease severity." (PMID 37863263, 2023). "Recent studies have shown that PRMT2 expression and histone H3 methylation at arginine 8 are correlated with disease severity in glioblastoma multiforme, hepatocellular carcinoma, and renal cell carcinoma." (PMID 37863263, 2023). "Delving deeper into heteromeric PRMT2 complex activities will be imperative to understanding their biological implications and involvement with diseases like glioblastoma multiforme, hepatocellular carcinoma, and renal cell carcinoma." (PMID 37863263, 2023). "PRMT2 expression is upregulated in glioblastoma multiforme (GBM) and in hepatocellular carcinoma (HCC) tissues and cells." (PMID 34833139, 2021). "PRMT2 expression is elevated in glioblastoma and is correlated with tumor grade." (PMID 34006904, 2021). "Therefore, we assessed how PRMT2 depletion affected the self-renewal of glioblastoma stem cells (GSCs)." (PMID 30382083, 2018). "Although the regulatory function of PRMT2 in tumourigenesis is fairly established, it is particularly noted for connecting histone H3R8 asymmetric dimethylation to oncogenic activation and glioblastoma development." (PMID 40078091, 2025). "The silencing or inactivation of PRMT2 inhibits GBM cell growth and glioblastoma stem cell self-renewal in vitro, and suppresses orthotopic tumor growth, accompanied with significant deregulation of genes mainly associated with cell cycle progression and pathways in cancer." (PMID 30382083, 2018). "Here, the authors show that PRMT2 is highly expressed in Glioblastoma multiforme (GBM) and provide evidence that PRMT2 acts as a transcriptional co-activator for oncogenic gene expression programs, at least partly dependent on its H3R8me2a activity, in GBM pathogenesis." (PMID 30382083, 2018).
Obesity (5 papers, 2017 to 2024). Accumulation of substantial excess body fat. "PRMT2 is associated with disorders of energy metabolism, obesity resistance and leptin sensitivity." (PMID 37144154, 2023). "The observation that PRMT2 null mice are leaner than wildtype animals, associated with perturbed energy metabolism, resistance to obesity and enhanced leptin sensitivity, suggested an involvement of PRMT2 in the regulation of feeding via a leptin-dependent pathway." (PMID 34833139, 2021). "Since SDMA originates from the PRMT2 isoform, we speculate that obesity affects PRMT activity and that bariatric surgery primarily reverses this activity (i.e., NMMA and ADMA production)." (PMID 34822417, 2021). "Interestingly, PRMT2 knockout mice are lean, less prone to develop diet-induced obesity and have reduced glycogen stores suggesting that PRMT2-dependent methylation of STAT3 on R31 plays a positive role in obesity." (PMID 39680066, 2024). "In addition to phosphorylation, leptin-induced STAT3 methylation by protein arginine N-methyltransferase 2 (PRMT2) was also shown to occur, and PRMT2−/− mice are lean, hypophagic, have reduced serum leptin levels and are more resistant to diet-induced obesity (DIO) compared to wild-type littermates." (PMID 28270795, 2017).
atherosclerosis (4 papers, 2015 to 2024). A disease characterized by the build-up of fatty material and calcium deposition in the arterial wall resulting in partial or complete occlusion of the arterial lumen. "Thus, the loss of PRMT2 is causally linked to impaired atherosclerosis regression via a heightened inflammatory response in macrophages." (PMID 35835907, 2022). "Because PRMT2 expression is reduced in cells in hyperglycemia, we wanted to determine whether PRMT2 plays a causal role in the impairment of atherosclerosis regression in diabetes." (PMID 35835907, 2022). "Nonetheless, it would be interesting in future studies to determine whether the regression of atherosclerosis is also impaired in dietary or genetic mouse models of Type 2 diabetes and whether this is associated with reduced PRMT2 expression in plaque macrophages." (PMID 35835907, 2022). "Thus, PRMT2-deficiency reduced the ability of macrophages to migrate out of the plaque under normoglycemic conditions, potentially contributing to the impaired regression of atherosclerosis." (PMID 35835907, 2022). "Our study is the first to illustrate a direct link between PRMT2 and the regression of atherosclerosis in diabetes and represents exciting progress in the study of arginine methyltransferases in CHD." (PMID 35835907, 2022). "We, therefore, examined the consequence of deleting PRMT2 in myeloid cells during the regression of atherosclerosis in normal and diabetic mice." (PMID 35835907, 2022). "That PRMT2 expression was lower in myeloid cells in plaques from human subjects with diabetes supports the relevance of our findings to human atherosclerosis." (PMID 35835907, 2022). "In fact, we found that the deletion of PRMT2 in myeloid cells under normoglycemic conditions phenocopied the impaired atherosclerosis regression in hyperglycemic mice by reducing the ability of macrophages to migrate out of the plaque." (PMID 35835907, 2022). "Given our findings that macrophages show decreased ABCA1-mediated efflux upon reduction of PRMT2, studies that examine the effects of PRMT2 directly on atherosclerosis and diabetes are now warranted but beyond the scope of this study." (PMID 26288135, 2015). "We would predict that mice with macrophages devoid of PRMT2 would be more prone to atherosclerosis due to their inability to efficiently efflux cholesterol." (PMID 26288135, 2015). "Approaches to increase PRMT2 expression in diabetes/hyperglycemia could facilitate atherosclerosis regression and reduce CHD." (PMID 35835907, 2022). "Thus, the expression of PRMT2 is a key factor in promoting atherosclerosis regression, and conversely, its reduction contributes to impaired atherosclerosis regression." (PMID 35835907, 2022). "Although PRMT2 appears to play a major role in the regression of atherosclerosis in diabetes, other factors have been reported to either enhance or repress the regression of atherosclerosis in diabetes." (PMID 35835907, 2022). "Work performed by other groups suggests a somewhat different scenario where deletion of PRMT2 has a protective effect with respect to atherosclerosis as Prmt2-/- mice fed a high fat diet were resistant to weight gain and had favorable lipid profiles, glucose tolerance tests and insulin levels." (PMID 26288135, 2015). "To test this hypothesis, we examined whether the myeloid-specific deletion of Prmt2 would impair the regression of atherosclerosis in normoglycemic conditions, thus mimicking the decrease in the regression of atherosclerosis in WT mice under diabetic conditions." (PMID 35835907, 2022). "Given that PRMT2 has the potential to repress inflammation and increase cholesterol efflux pathways, we hypothesized that the reduced expression of PRMT2 by high glucose is a key determinant of impaired atherosclerosis regression in diabetes." (PMID 35835907, 2022).
atherosclerosis (continued). "Indeed, we observed lower PRMT2 expression in myeloid cells of plaques from humans with diabetes compared to those without diabetes, supporting the relevance of our findings in mouse models to human atherosclerosis." (PMID 35835907, 2022). "PRMT2 represents a glucose-sensitive factor controlling ABCA1-dependent cholesterol efflux, while it has potential to explain atherosclerosis in diabetic patients." (PMID 37144154, 2023). "Remarkably, we found significant impairment of atherosclerosis regression under normoglycemic conditions in mice lacking PRMT2 (Prmt2−/−) in myeloid cells that mimic the decrease in regression of atherosclerosis in WT mice under diabetic conditions." (PMID 35835907, 2022). "Thus, future studies directed at elucidating PRMT2 substrates, regulation and in vivo function in macrophages would be crucial for understanding the role PRMT2 plays in LXR-mediated regulation of Abca1 in diabetes and atherosclerosis." (PMID 26288135, 2015). "Thus, PRMT2 represents a glucose-sensitive factor that plays a role in LXR-mediated ABCA1-dependent cholesterol efflux and lends insight to the presence of increased atherosclerosis in diabetic patients." (PMID 26288135, 2015).
glioma (4 papers, 2018 to 2024). A benign or malignant brain and spinal cord tumor that arises from glial cells (astrocytes, oligodendrocytes, ependymal cells). "Quantification of PRMT2 in 21 cases of glioma of different grades by immunohistochemistry showed increased PRMT2 expression in higher grade samples." (PMID 33404912, 2021). "Consistently, IHC staing of CCNB1, CCND1, and CDK4 of the 21 glioma specimens confirmed that the protein expression levels of these cell cycle gene are correlated with PRMT2 in different grades of gliomas." (PMID 30382083, 2018). "Together, this study demonstrates that PRMT2 acts as a transcriptional co-activator for oncogenic gene expression programs in GBM pathogenesis and provides a rationale for PRMT2 targeting in aggressive gliomas." (PMID 30382083, 2018). "PRMT2, another overexpressed PRMT protein, confers poor patient prognosis, and knockout of PRMT2 causes reductions of phosphorylated STAT3, AKT, and MAPK in glioma cell lines." (PMID 38183103, 2024). "We observed a clear nuclear enrichment of PRMT2 in high-grade gliomas." (PMID 30382083, 2018). "In addition, the elevated expression of PRMT1, PRMT2, PRMT4, and PRMT6 predicts poor prognosis in glioma patients." (PMID 30382083, 2018). "Interestingly, the expression levels of PRMT1, PRMT2, PRMT4, and PRMT6 in low-grade gliomas are significantly higher in IDH1/2 wild-type (WT) subgroups than the subgroups with the IDH1/2 mutations." (PMID 30382083, 2018).
breast tumors (3 papers, 2016 to 2022). "In effect, the expression of PRMT2 and its splice variants is increased in breast tumors compared to normal tissues." (PMID 27556302, 2016). "Allof the PRMT2 isoforms showed increased expression in breast tumor compared to normal tissues and are all able to enhance ERα-mediated transactivation activity in the presence of estradiol." (PMID 34833139, 2021). "Thus, PRMT2 mRNA alternative splicing could be at least partially responsible for breast tumor development." (PMID 34833139, 2021).